DDT (D-dopachrome tautomerase)
Description:
Tautomerization of D-dopachrome with decarboxylation to give 5,6-dihydroxyindole (DHI).
Synonyms: DDCT; MIF2; MIF-2; D-DT
Tractability: Small molecule: a structure with a bound ligand is known. PROTAC: ubiquitination databases record sites on it; its protein half-life has been measured.
Target class: Enzyme; Lyase
Gene: Protein-coding gene on chromosome 22 (23,970,542 to 23,980,525, reverse strand). Ensembl gene ENSG00000099977.
Subcellular location: Cytoplasm
Subcellular location (Human Protein Atlas): Mitochondria
Gene Ontology:
Molecular function: cytokine receptor binding; D-dopachrome decarboxylase activity; phenylpyruvate tautomerase activity; dopachrome isomerase activity
Biological process: negative regulation of macrophage chemotaxis; positive regulation of ERK1 and ERK2 cascade; positive regulation of tumor necrosis factor production; positive regulation of inflammatory response
Cellular component: extracellular exosome; extracellular region; cytoplasm
Genetic constraint (gnomAD): Loss-of-function variants: 4 observed, 2.76 expected, observed/expected ratio (o/e) 1.45, 90% interval 0.63 to 1.93. That is too few expected variants to judge how well the gene tolerates losing a copy. Missense variants: 32 observed, 31.12 expected, observed/expected ratio (o/e) 1.03, 90% interval 0.77 to 1.38. Synonymous variants: 11 observed, 10.61 expected, observed/expected ratio (o/e) 1.04, 90% interval 0.65 to 1.67.
Homologues: Orthologues: dog DDT (85% identical), pig DDT (81% identical), mouse Ddt (74% identical), tropical clawed frog ddt (64% identical), zebrafish ddt (53% identical). Paralogues in human: DDTL (84% identical), MIF (33% identical).
Diseases named in the same sentence as DDT in open-access papers:
DDT is named in the same sentence as 30 diseases in open-access papers, as found by Europe PMC text mining. Sharing a sentence is not in itself a finding about the gene and the disease. The quoted sentences say what the papers report.
melanoma (4 papers, 2014 to 2025). A malignant, usually aggressive tumor composed of atypical, neoplastic melanocytes. "Genetic, transcriptomic, and proteomic analyses of DDT, CD74:MIF, and CD74:DDT in patients with melanoma can further shed light on the differential expression among varying disease stages, tumor subtypes, mutational statuses, and ICI use." (PMID 39028303, 2024). "This analysis also does not factor in epigenetic regulators of MIF expression or expression of the MIF homolog DDT (or MIF-2), which also engages the cognate MIF receptor CD74 and is expressed in many tumor types, including melanoma." (PMID 41122966, 2025).
Williams-Beuren syndrome (2 papers, 2020 to 2024). "This protein contains the WAC_Acf1_DNA_bd (ATP-utilizing chromatin assembly and remodeling) region, as well as the DDT, WHIM1 (WSTF, HB1, Itc1p, and MBD9 motif 1), and WSD (Williams-Beuren syndrome DDT (WSD), D-TOX E motif) domains for histone recognition and DNA binding." (PMID 39796039, 2024). "These domains are DDT (DNA binding homeobox and Different Transcription factors) and WSD (Williams-Beuren syndrome DDT motif) domains." (PMID 32428081, 2020).
allergic disease (1 paper, 2025). An immune response that occurs following re-exposure to an innocuous antigen, and that requires the presence of existing antibodies against that antigen. "The results suggested that DdT may contain active components that can antagonize H1R, which is closely related to its mechanism of treating allergic diseases." (PMID 40520177, 2025).
atopic dermatitis (1 paper, 2025). "Dictamnine was the primary active component of DdT, which could regulate the degranulation of mast cells in atopic dermatitis mice and ameliorate inflammation in an oxazolone-induced dermatitis mouse model." (PMID 40520177, 2025).
Autoimmunity (1 paper, 2024). The occurrence of an immune reaction against the organism's own cells or tissues. "DDT, also referred to as MIF-2, is less understood, but may have overlapping roles in promoting tumorigenesis and autoimmunity given its shared binding to CD74, CXCR4 and CXCR7 receptors." (PMID 39028303, 2024).
cervical cancer (1 paper, 2021). A primary or metastatic malignant neoplasm involving the cervix. "D-dopachrome tautomerase (D-DT), a homolog of macrophage migration inhibitory factor (MIF), can promote the invasion of cervical cancer cells when it is overexpressed." (PMID 33671013, 2021).
COVID-19 (1 paper, 2023). A disease caused by infection with severe acute respiratory syndrome coronavirus 2. "However, no studies have yet analyzed the role of the MIF homologue, D-dopachrome tautomerase (D-DT), and of its receptors in COVID-19." (PMID 37568438, 2023).
diabetic kidney disease (1 paper, 2018). Progressive kidney disorder caused by vascular damage to the glomerular capillaries, in patients with diabetes mellitus. "CD74 is a multifunctional protein and a receptor for Macrophage Migration Inhibitory Factor (MIF) and MIF-2 / D-dopachrome tautomerase (DDT) cytokines, upregulated in diabetic kidney disease." (PMID 29924850, 2018).
liver fibrosis (1 paper, 2015). "These biomarkers are acetoacetyl-CoA synthetase (AACS), dipeptidyl-peptidase 4 (DPP4), d-dopachrome tautomerase (DDT), glutamine synthetase (GLUL), and glutathione S-transferase (GST); particularly, the plasma DPP4 and GST levels were highly associated with CCl4-induced liver fibrosis." (PMID 26491462, 2015).
multiple sclerosis (1 paper, 2019). A progressive autoimmune disorder affecting the central nervous system resulting in demyelination. "For this purpose, we carried out a transcriptomic analysis of MIF, DDT, and their receptors and co-receptors in CIS patients with subsequent rapid development of Clinically Definite Multiple Sclerosis (CDMS)." (PMID 31581595, 2019).
neuroblastoma (1 paper, 2019). Neuroblastoma (NB) is the most common solid, extracranial childhood tumor. "We have also shown that the inhibition of the expression of both MIF and DDT, by short interfering RNA, in vincristine-resistant NKF-NB-3 neuroblastoma cells, is able to revert drug resistance." (PMID 31635049, 2019).
ovarian carcinoma (1 paper, 2025). A malignant neoplasm originating from the surface ovarian epithelium. "We found that the expression of BANF1, CDK2AP2, DDT, LRIG1, MRPL4, and S100A13 was upregulated in ovarian cancer samples, and the expression of EPS8, NUCB2, PAF1, PMP22, RABGAP1L, and USO1 was upregulated in normal samples." (PMID 41000388, 2025).
serous ovarian cancer (1 paper, 2010). "That is, one group including: SSBP1, IFI6 DDT, IFI27, C11orf92, NFKBIA, TNXB, NEAT1 and TFG, was up-regulated in most patients with stage III serous ovarian cancer." (PMID 20969748, 2010).
skin cancer (1 paper, 2024). "Bulk-RNA sequencing of patient tumor samples from the Skin Cancer SPORE Biorepository was used to evaluate for differential gene expression of MIF, DDT, CD74, and selected inflammatory markers, and gene expression was correlated with patient survival outcomes." (PMID 39028303, 2024).
tumor (6 papers, 2007 to 2025). "Macrophage Migration Inhibitory Factor (MIF) and its homolog D-dopachrome Tautomerase (DDT) have been implicated as drivers of tumor progression across a variety of cancers." (PMID 39028303, 2024). "Here, we provide an overview of the involvement of both MIF and DDT in cancer, and we propose that blocking both cytokines is needed to obtain the maximum anti-tumor response." (PMID 36672343, 2023). "The analysis revealed that in the training set, the expression of BANF1, CDK2AP2, DDT, LRIG1, MRPL4, and S100A13 was significantly upregulated in tumor samples, and the expression of EPS8, NUCB2, PAF1, PMP22, RABGAP1L, and USO1 was higher in control samples (p < 0.05)." (PMID 41000388, 2025). "Likewise, no role in tumor progression has been assigned yet to DDT, a protein with homology to macrophage migration inhibitory factor (MIF)." (PMID 17553165, 2007).
cancer (5 papers, 2014 to 2024). A tumor composed of atypical neoplastic, often pleomorphic cells that invade other tissues. "MIF and DDT dysregulation have been implicated in most of the pathologic hallmarks of cancer, with downstream effects of proliferation, immune suppression, immune dysregulation, enhancement of angiogenesis and metastasis." (PMID 39028303, 2024). "Though MIF and DDT have been widely described in inflammation and autoimmunity, interest in these cytokines within oncology has also been relatively recent given their roles in driving cancer hallmarks and their overexpression across a variety of cancers." (PMID 38732068, 2024). "MIF and DDT play pivotal roles in multiple facets of cancer progression and possibly initiation." (PMID 38732068, 2024). "The macrophage migration inhibitory factor (MIF) family of cytokines, comprising MIF and DDT (also known as MIF2), are overexpressed in almost all cancer types, and their high expressions are related to a worse prognosis for the patients." (PMID 36672343, 2023). "Extensive experimental and computational research has unveiled intricate signaling mechanisms in MIF/DDT/CD74 pathways across diverse cancer types, shedding light on the complexity of canonical and non-canonical signaling processes within the TME." (PMID 38732068, 2024).
infectious disease (1 paper, 2023). A disorder directly resulting from the presence and activity of a microbial, viral, or parasitic agent in humans. "Macrophage migration inhibitory factor (MIF) and its homolog, D-dopachrome tautomerase (D-DT), are cytokines that play critical roles in the immune response to various infectious diseases." (PMID 38275363, 2023).
kidney disease (1 paper, 2018). "While MIF has been implicated in glomerular and tubulointerstitial injury, very little is known about D-dopachrome tautomerase (DDT), a second ligand for CD74, in kidney disease." (PMID 29924850, 2018).
DDT also shares sentences with these, for which no sentence is quoted: adenomyosis (2 papers); asthma (1); autoimmune disease (1); breast carcinoma (1); clear renal cell carcinomas (1); dermatitis (1); glioma (1); non-melanoma skin carcinoma (1); non-small cell lung carcinoma (1); rectal tumor (1); systemic sclerosis (1); viral infections (1).